ERBB4 (erb-b2 receptor tyrosine kinase 4)
Diseases named in the same sentence as ERBB4 in open-access papers (continued):
Sharing a sentence is not in itself a finding about the gene and the disease.
glioma (continued). "Through a series of cellular experiments and target exploration, we confirmed that circ_0001162/miR-936/ERBB4 axis was involved in the regulation of glioma development." (PMID 34057019, 2021). "In summary, the mRNA levels of EGFR and ERBB2 were higher in advanced and poorly differentiated gliomas; however, the mRNA levels of ERBB3 and ERBB4 were lower in advanced and poorly differentiated gliomas." (PMID 33892666, 2021). "The current findings revealed that circ_0001162 targeted miR-936 to regulate the expression of ERBB4, consequently promoting cell malignant behaviors (proliferation, colony formation, migration and invasion) to act as a proto-oncogene in glioma." (PMID 34057019, 2021). "ERBB4 was also reported to be accountable for the regulation of circ_0074026/miR-1304 axis in the oncogenesis of glioma." (PMID 34057019, 2021). "Analysis of the TCGA data and the CGGA RNA-seq data found that ERBB3 and ERBB4 were notably increased in IDH mutant gliomas, and the same result was found in the CGGA RNA-seq datasets." (PMID 33892666, 2021). "For example, circPITX1 sponged miR-1304 to modulate ERBB4 expression, leading to promotion in glioma progression." (PMID 32190004, 2020). "Other remarkable pathways in this group were leukocyte extravasation signaling, glioma signaling, ERBB4 signaling, and chemokine signaling, as well as Wnt/β-catenin SP which was also observed in the PR group." (PMID 28892521, 2017). "ERBB4 protein is a tyrosine-protein kinase and a member of the epidermal growth factor receptor subfamily, which contributes to glioma pathogenesis." (PMID 26614510, 2016). "It is possible that ERBB4 and PLCβ1, as neuron predominant proteins, contribute to glioma tumorigenesis or progression." (PMID 26614510, 2016). "According the previous results, ERBB-2 and ERBB-3 mRNAs were detected only in a few high-grade gliomas, while ERBB-4 expression was most pronounced in low-grade gliomas." (PMID 24986561, 2014). "Moreover, experiments showed that PLC-β1 signal intensity was consistent with ERBB4 in low-grade and high-grade glioma tumors." (PMID 37576896, 2023). "In addition, there is also a correlation between the expression of PLC-β1 and glioma PN signature gene ERBB4." (PMID 37576896, 2023). "Comparison of ErbB4 isoform-specific expression in low versus high-grade glioma may be more pertinent." (PMID 36119496, 2022). "In the current report, we first discovered that circ_0001162 could affect the oncogenesis of glioma by targeting miR-936 to modulate the level of ERBB4." (PMID 34057019, 2021). "The miR-936/ERBB4 axis was responsible for the oncogenic role of circ_0001162 in glioma." (PMID 34057019, 2021). "Taken together, circ_0001162 promoted the evolvement of glioma by the miR-936/ERBB4 axis." (PMID 34057019, 2021). "Compared to the previous studies, this study provided a specific circ_0001162/miR-936/ERBB4 signal axis in glioma progression and might lay the great foundation for circRNA research of glioma in the future." (PMID 34057019, 2021). "For example, circ_0001162 is involved glioma development via the miR-936/ERBB4 axis." (PMID 34617876, 2021). "Herein, we hypothesized that miR-936 was a miRNA target for circ_0001162 and ERBB4 acted as a target gene for miR-936, and circ_0001162 could affect the level of ERBB4 via targeting miR-936 in glioma." (PMID 34057019, 2021). "Circ_0001162 was hypothesized as a miR-936 inhibitor to regulate the expression of ERBB4 in glioma progression." (PMID 34057019, 2021). "CircPITX1, produced via splicing of PITX1, could aggravate glioma progression by miR-1304/ERBB4 axis, acting as an indicator of poor prognosis of patients with glioma." (PMID 32190004, 2020). "To determine whether ERBB4 is expressed in GBM, we measured total ERBB4 expression in GBM samples derived from patients diagnosed with World Health Organization WHO grade III or IV primary glioma, NNB and Ref Brain." (PMID 30044378, 2018).
glioma (continued). "With this goal in mind, an initial analysis of copy number data from 60 glioma cell lines from the CCLE database revealed that the copy number distribution for ERBB4 is shifted to the left of normal copy number of 2 for diploid cells, signifying copy number loss or deletion." (PMID 29342193, 2018). "Here, we use publicly available data to explore copy number variation of ERBB4 in gliomas." (PMID 29342193, 2018). "In addition, our analysis demonstrates that PLCβ1 gene expression level correlates the best with glioma PN signature gene ERBB4." (PMID 26614510, 2016). "Moreover, a study by Andersson and colleagues showed that ErbB4 mRNA and protein expression was highest in low-grade gliomas, compared with higher grade tumors, suggesting that ErbB4 may act as a tumor suppressor." (PMID 36119496, 2022). "Additionally, miR-936 inhibited the glioma development via targeting ERBB4." (PMID 34057019, 2021). "Similarly, we identified that miR-936 was an anti-tumor factor in glioma by targeting ERBB4." (PMID 34057019, 2021). "Through literature research, we screened out five mRNAs (SPARC, YY1, ERBB4, MAP3K2, and FZD6) that are highly expressed in glioma tumor tissues and promote glioma progression." (PMID 37554539, 2023). "The mRNA expression of ERBB3 and ERBB4 in gliomas was notably positively correlated with the level of CD4+ T cell infiltration (ERBB3, r = 0.1200, p = 0.0016, ERBB4, r = 0.09663, p = 0.0114)." (PMID 33892666, 2021). "However, it remains unclear what role, if any, ERBB4 plays in the progression of gliomas." (PMID 29342193, 2018). "Both microarray data of ERBB4 and Olig2, two known PN subtype signature genes, show significantly different expression levels between grade III and IV gliomas in GDS1815 dataset (p = 0.01 and 0.005, respectively)." (PMID 26614510, 2016). "Perhaps a multi-faceted approach with both ErbB4 inhibitors and EGFR inhibitors could prove more consistently effective against high-grade gliomas." (PMID 36119496, 2022). "The mechanisms by which ErbB4 activation increases high-grade glioma aggressiveness are not yet understood." (PMID 36119496, 2022). "Among them, ERBB4 belongs to the ERBB receptor family and plays an important role in the development of the nervous system, and the ERBB growth factor receptor is considered to be a key signaling pathway for many human tumors, including glioma." (PMID 34863158, 2021). "Recently, four groups reported different circPITX1-mediated ceRNETs in glioma cells, i.e., circPITX1/miR-518a-5p/IL17RD, circPITX1/miR-1304/ERBB4, circPITX1/miR-379-5p/mitogen-activated protein kinase 2 (MAP3K2), and circPITX1/miR-329-3p/NIMA-related kinase 2 (NEK2)." (PMID 33995499, 2021). "Five out of the ten top hub nodes from general glioma networks from StringDB and BioGRID are matching genes containing erb-b2 receptor tyrosine kinase 2 (HER2), erb-b2 receptor tyrosine kinase 4 (HER4), cyclin D3 (CCND3), TEK tyrosine kinase (TEK), and transforming growth factor alpha (TGFA)." (PMID 31952211, 2020). "Copy number analysis of all glioma cell lines in CCLE revealed that there is a potential mutually exclusive relationship between loss in ERBB4 and loss in NRG1 as ERBB4 and NRG1 copy number loss never occur simultaneously." (PMID 29342193, 2018). "While ERBB4 CNV in glioma cell lines turned out to be an artifact, that is not to say that other CNV’s important in the development of cancer may not be uncovered using this method." (PMID 29342193, 2018).
ovarian carcinoma (32 papers, 2010 to 2025). A malignant neoplasm originating from the surface ovarian epithelium. "Expression of HER4 (ERBB4) has been associated with chemoresistance in ovarian cancer and this decreased on carboplatin treatment." (PMID 26964739, 2016). "Bioinformatic analysis revealed that NDRG1, CYBRD1, and MT2A expressions upregulated and were associated with poor prognosis of ovarian cancer patients in the platinum-based treatment group, whereas upregulation of ERBB4 and ANK3 correlated with improved prognosis." (PMID 38987777, 2024). "Notably, it was recently shown that expression of CYT-1 ERBB4 is associated with poor survival from ovarian cancer." (PMID 25516216, 2014). "Furthermore, higher ErbB4 expression has been reported to associate with improved disease-free survival in ovarian cancers." (PMID 21364581, 2011). "Interestingly, established ovarian cancer cell lines that express high ErbB4 protein level have all been derived from platinum-refractory tumours, raising the possibility that ErbB4 expression may associate with the development of platinum resistance." (PMID 21364581, 2011). "Many reports have highlighted the role of ERBB4 in cancer, and it is also related to the pathogenesis and prognosis of ovarian cancer." (PMID 38534733, 2024). "While some studies suggest that ERBB4 is a poor prognostic factor in ovarian cancer, others indicate that is inhibits cancer growth." (PMID 38987777, 2024). "Rearrangements of the ERBB2 gene have been found in breast as well as gastric cancers and ERBB4 fusions have been reported in lung adenocarcinomas and ovarian cancer cell lines." (PMID 37168365, 2023). "ERBB4 is the least investigated of all the ERBB family members in ovarian cancer, especially with regards to the effects of BTC." (PMID 27129169, 2016). "On the other hand, an ErbB4 antibody that blocks ErbB4 and NRG1 interaction appeared to have a stimulatory effect in some of the ovarian cancer cell lines tested, suggesting a possible role for ErbB4 in growth inhibition in these cells." (PMID 21364581, 2011). "Cytoplasmic staining of ErbB4 was detected in 89–93% of 53 unselected ovarian cancer tumours using two different anti-ErbB4 antibodies directed to either the cytoplasmic or the extracellular domain of ErbB4." (PMID 21364581, 2011). "Notably, research on ERBB4 in ovarian cancer primarily focuses on benign ovarian tissue and malignant ovarian tumors." (PMID 38987777, 2024). "Currently, the role of ERBB4 in the regulation of ovarian cancer cell growth is controversial." (PMID 38987777, 2024). "ERBB3 and ERBB4 have been shown to be upregulated in chemoresistant ovarian cancer and upregulation was observed in Indian ovarian cancer, which might serve as a potential therapeutic target." (PMID 37091785, 2023). "Furthermore, the expression level of ERBB4 in normal ovarian tissues was significantly lower than that in ovarian cancer tissues (P<0.001)." (PMID 36185201, 2022). "Previous studies have demonstrated that the native ligand of epidermal growth factor receptor (EGFR) and ErbB4, heparin-binding EGF-like growth factor (HB-EGF), plays a critical role in the progression of ovarian cancer and is associated with prognosis of ovarian cancer." (PMID 30937184, 2019). "However, BTC-induced SKOV3 and OVCAR5 cell migration was only partially inhibited by AG1478, suggesting a potential role of ERBB4 in BTC-induced ovarian cancer migration." (PMID 27129169, 2016). "Thus, the roles of BTC and ERBB4 in ovarian cancer are likely complex, and warrant further investigation." (PMID 27129169, 2016). "Notably, ERBB3 and ERBB4 are the predominantly expressed EGFR family members in ovarian cancer, where they showed marked expression in 76% and 98% of all cases in a recent study." (PMID 26745281, 2016).
ovarian carcinoma (continued). "Together, these observations suggest that the role of ErbB4 in ovarian tumours may be complicated and, to date, its function in both early ovarian cancer development and late-stage disease remains undefined." (PMID 21364581, 2011). "In serous ovarian cancer, the ERBB4 CYT-1 variant we expressed in Ba/F3 cells was identified as independent prognostic factor for survival, and may cooperate with NRG1 autocrine signaling to support ERBB3-mediated ovarian cancer cell proliferation in vivo." (PMID 26745281, 2016). "Interestingly, mounting evidence suggests that different isoforms of ERBB4 may correlate with different clinical outcomes in ovarian cancer patients." (PMID 27129169, 2016). "The clinical significance of ErbB4 in ovarian cancer is currently unknown." (PMID 21364581, 2011). "Consistent with a role of ERBB4 as heterodimerizing partner, tyrosine phosphorylation of ERBB3 was widely detectable in ovarian cancer samples." (PMID 26745281, 2016). "miR-193a induced the inhibition of DNA synthesis and apoptosis by targeting genes including ARHGAP19, CCND1, ERBB4, KRAS, MCL1, indicating a tumor suppressive role of this miRNA in epithelial ovarian cancer cells." (PMID 23588298, 2013). "Our results suggested that the simultaneous activation of multi-RTK (EGFR, ERBB2, ERBB4, MET and/or AXL) in individual ovarian cancer contribute to the drug resistance to individual RTK inhibitors in ovarian cancer." (PMID 21962244, 2011). "The HSP90 inhibition led to the dephosphorylation and degradation of EGFR, ERBB2, ERBB4, MET and AXL in various ovarian cancer cells." (PMID 21962244, 2011). "Herein, we demonstrate co-activation of multiple RTKs (EGFR, ERBB2, ERBB4, MET and/or AXL) in individual ovarian cancer cell lines and primary tumors." (PMID 21962244, 2011). "We show that its synergistic anti-cancer effect, when combined with paclitaxel, is independent of EGFR, ERBB2, or ERBB4 antagonism in human ovarian cancer cell models." (PMID 34347777, 2021).
colorectal cancer (25 papers, 2006 to 2025). A primary or metastatic malignant neoplasm that affects the colon or rectum. "HER4 (ErbB4), though less extensively studied, has also been linked to enhanced proliferation, survival, and metastatic potential in colorectal cancer cells." (PMID 41515404, 2025). "Expression of the KITENIN/ErbB4 oncogenic complex is associated with metastasis of colorectal cancer to distant organs and lymph nodes and is linked with poor prognosis and poor survival." (PMID 39030594, 2024). "A study on colorectal cancer cells revealed that high expression of ErbB4 leads to activation of the ErbB4-Akt1-Lamin A/C pathway, resulting in the phosphorylation of lamin A/C." (PMID 39768219, 2024). "All these kinases displayed mutations in more than 6% of CDX2-suppressed colorectal cancers in the TCGA cohort, and some receptor tyrosine kinases, including EGFR, ERBB3, ERBB4, RET, ROS1, and ALK, showed even higher mutation rates in these cancers." (PMID 39452477, 2024). "Here, we used in vitro and in silico methods to test the ability of chrysophanol, a molecule of natural origin, to suppress the progression of colorectal cancer by targeting the KITENIN/ErbB4 complex." (PMID 39030594, 2024). "Meanwhile, ERBB4 is highly expressed in colorectal cancer cells and augments colorectal carcinogenesis." (PMID 34667159, 2021). "In this study, we demonstrated frequent methylation of the ErbB signalling network (PIK3CD, PKCΒ, ERBB4, PAK7) in colorectal cancer (CRC)." (PMID 25366420, 2015).
Obesity (25 papers, 2012 to 2025). Accumulation of substantial excess body fat. "Given this, it is much more likely that it is deficiency of ErbB4 in the hindbrain- and spinal cord-projecting neurons that are responsible for the obesity phenotype." (PMID 37669858, 2023). "GWAS studies identify the receptor tyrosine kinase ErbB4 as a risk gene for obesity and for major depression disorders." (PMID 37669858, 2023). "For NLS, ERBB4 was associated with obesity on subjects from UK Biobank, which contained 339,244 individuals." (PMID 38075049, 2023). "Genetic studies have indicated that ErbB4 is closely associated with obesity and type 2 diabetes, but its specific role in metabolic syndrome remains poorly understood." (PMID 37060105, 2023). "Studies have shown that the receptor tyrosine kinase ErbB4 is a risk gene for both obesity and major depression disorder." (PMID 37669858, 2023). "ErbB4-null mice are susceptible to diet induced obesity, with increased fasting plasma glucose and insulin and reduced liver function." (PMID 37669858, 2023). "Variants in ErbB4 have been associated with BMI in an African American population and associated with severe obesity in a Han Chinese population." (PMID 37669858, 2023). "Perturbations in NRG1/ErbB4 function have been associated with various neuropsychiatric disorders, resilience to stress, and obesity/metabolic syndrome." (PMID 35220393, 2022). "Genetic studies have demonstrated strong associations between single-nucleotide polymorphisms in the ErbB4 gene and obesity." (PMID 35220393, 2022). "These anti-obesity effects also necessitated the presence of ErbB4, as ErbB4 deficiency led to severe inflammation, increased lipogenesis, and increased serum leptin levels." (PMID 36703934, 2022). "Considering that ErbB4 is a risk gene for both obesity and major depression disorder, our study provides insight into pathophysiological mechanisms of depression-associated obesity." (PMID 37669858, 2023). "We injected Oxt peptide directly to Oxt‐shCtrl or Oxt‐shErbB4 mice and found that Oxt could rescue obesity caused by ErbB4 knockdown in PVN neurons." (PMID 37060105, 2023). "Notably, while ErbB4 deletion predisposes mice to metabolic alterations implicated in obesity, NRG1 administration is known to improve metabolic health in obese mice by lowering blood glucose, improving insulin sensitivity, and reducing caloric intake." (PMID 35220393, 2022). "Interestingly, ErbB4 is one of the genes linked to obesity and diabetes, as shown by studies of various International Consortiums such as the ADIPOGen and GENIE Consortiums." (PMID 32655416, 2020). "Because Nrg4 transgenic mice exhibited reduced fat mass and elevated energy expenditure, our findings raise the possibility that Nrg4/ErbB4 signaling may be a genetic factor for human obesity and its associated metabolic disorders." (PMID 28752050, 2017). "Overexpression of Nrg4 in the paraventricular nucleus (PVN) of the brain protects against HFD-induced obesity, whereas ErbB4 knockdown in oxytocin neurons accelerates obesity." (PMID 40243151, 2025). "Here, we observed that ErbB4 was abundantly expressed in the hypothalamus and that phosphorylation of ErbB4 was reduced in diet induced obesity (DIO) mice." (PMID 37060105, 2023). "Overexpression of ErbB4 in the PVN protects against obesity, whereas its knock down in oxytocin (Oxt) neuron accelerates obesity." (PMID 37060105, 2023). "ErbB4 whole‐body deletion in mice led to the development of obesity and related metabolic dysfunction, but the specific mechanism by which ErbB4 regulates metabolism is still unclear." (PMID 37060105, 2023). "Authors provide reasonably convincing data that loss of ErbB4 in PVH neurons, including oxytocin-expressing PVH neurons, causes obesity that is likely due to a decrease in energy expenditure." (PMID 37669858, 2023).